NOTCH1 (notch receptor 1)
Diseases named in the same sentence as NOTCH1 in open-access papers (continued):
Sharing a sentence is not in itself a finding about the gene and the disease.
cervical carcinoma (continued). "Targeting JAG1-induced Notch1 activation, by Notch1 RNA interference or by a γ-secretase inhibitor, suppressed cervical cancer invasiveness." (PMID 25309874, 2014). "Overexpression of JAG1 in cervical cancer samples was coupled with the downregulation of Mfng, a negative regulator of the Jagged-Notch1 interaction." (PMID 25309874, 2014). "A study on a human cervical cancer cell line found that Notch1 activates NF-κB by interacting with the IκB kinase (IKK) signal." (PMID 23599800, 2013). "Immunohistochemical analysis of archival tissue suggests a correlation between RhoC and Notch1 expression in human cervical carcinoma tissues." (PMID 19953094, 2010). "This study has provided evidence to suggest that RhoC is an effector of Notch1 in cervical carcinoma." (PMID 19953094, 2010). "To further corroborate our findings in a clinical setting, we examined the expression of RhoC and its relationship with Notch1 in archival cervical carcinoma specimens using immunohistochemical technique." (PMID 19953094, 2010). "However, the specific regulatory mechanisms of NOTCH1 in cervical cancer progression and therapeutic resistance, as well as its impact on the tumor immune microenvironment, remain to be further elucidated." (PMID 41306984, 2025). "This indicates that NOTCH1 may drive the overall progression of cervical cancer by regulating the cell cycle process of specific malignant cell subsets." (PMID 41306984, 2025). "Therefore, in this study, we further explored the relationship between NOTCH1 and the radiosensitivity of cervical cancer." (PMID 41306984, 2025). "Thus, in cervical cancer, NOTCH1 expression promotes tumorigenesis in early disease stages, whereas it exerts a tumor suppressive role in late disease stages." (PMID 41009728, 2025). "This study clarifies NOTCH1’s role in promoting cervical cancer progression and reducing radiosensitivity, with has-miR-449a as a negative regulator, providing targets for optimizing cervical cancer radiotherapy." (PMID 41306984, 2025). "Therefore, this study employs multi-omics strategies, including scRNA-seq and high-throughput sequencing, combined with in vitro and in vivo experimental models to explore the role of NOTCH1 in cervical cancer." (PMID 41306984, 2025). "The results showed that Jagged1 protein on MSC-sEV can bind to NOTCH1 on cervical cancer cells, activate NOTCH signaling, and promote squamous differentiation levels in CaSki cells, thus inhibiting the growth, proliferation and migration abilities of CaSki cells." (PMID 37994984, 2023). "In addition, a correlation was established between Notch-1 signalling and Bcl-2 family members in cervical cancer cells." (PMID 38138866, 2023). "miR-34c-5p represses Notch1 and inhibits invasion and metastasis of cervical cancer." (PMID 35342412, 2022). "miR-34c-5p is able to inhibit Notch1 and represses invasion and metastasis in cervical cancer." (PMID 35342412, 2022). "Therefore, in this study, we performed several in vitro assays to gain detailed insight about the apoptotic inducing effect of rutin as well as its modulatory effect on Notch-1 and Hes-1 in cervical cancer cells." (PMID 34440505, 2021).
cervical carcinoma (continued). "Additionally, it has been observed that NOTCH1 is significantly reduced in HPV-positive cervical carcinoma cells as expression of activated NOTCH1 results in strong growth inhibition of these cells via down-modulation of transcription of the E6/E7 viral genes." (PMID 34298667, 2021). "However, it is worth mentioning that hyperactivation of Notch1 has been indicated as oncogenic in some subsets of cervical cancer, suggesting a contrasting role of Notch in this context." (PMID 34680255, 2021). "The authors claim that this combination could inhibit Notch-1 expression and downstream protein synthesis in in vitro and in vivo cervical cancer." (PMID 34683855, 2021). "These genes, particularly CEBPD, SLPI, KRT16, and NOTCH1, may serve as potential biomarkers at the mRNA level for the course of cervical cancer development, and warrant further study as it relates to understanding HPV-dependent carcinogenesis." (PMID 34944802, 2021). "Therefore, further studies are needed to elucidate the precise molecular mechanisms by which ST3Gal IV modulates the Notch1/p21/CDKs signaling pathway in cervical cancer." (PMID 33598419, 2020). "The overexpression of Notch1 signaling proteins in cervical cancer suggested that Notch1 may promote tumor progression." (PMID 33598419, 2020). "Conversely, other studies have shown that Notch1 has a tumor suppressive effect in cervical cancer." (PMID 31976596, 2020). "Our data provide a reciprocal regulation mechanism between IDO1 and Notch1 expression in cervical cancer cells and suggest that the IDO1 inhibitors may potentially be used as radiosensitizers." (PMID 32545442, 2020). "Notch1 also reduces cell proliferation in cervical cancer cell lines through E6 and E7 oncogenes." (PMID 31689961, 2019). "Notch-1 signaling pathway is involved in the occurrence and development of cervical cancer." (PMID 31417656, 2019). "We conclude that Notch-1 could be one of the targets of curcumin-PDT in the treatment of cervical cancer." (PMID 31417656, 2019). "Therefore, we have good reasons to suspect that Notch-1 is one of the key targets for curcumin-PDT in the treatment of cervical cancer." (PMID 31417656, 2019). "In conclusion, this study successfully demonstrated that Curcumin-PDT combined with DAPT could inhibit the expression of Notch-1 and its downstream related proteins in cervical cancer in vitro and in vivo." (PMID 31417656, 2019). "Curcumin-PDT and DAPT both inhibited Notch1 mRNA expression in Me180 cervical cancer cells." (PMID 31417656, 2019). "Curcumin-PDT and DAPT both inhibited Notch1 mRNA expression in cervical cancer xenografts." (PMID 31417656, 2019). "It is worth to mention that the protein Atlas database report a moderate NOTCH1 immunoexpression in cervical cancer, with a heterogeneous localization in the cell; this is opposite to our results since we found a diminished NOTCH1 expression in cervical cancer." (PMID 29721172, 2018). "Besides, cytoplasmic NUMB expression was associated with a decrease in nuclear NOTCH1 expression in cervical cancer samples, suggesting the potential regulation of NUMB over NOTCH1, as previously suggested." (PMID 29721172, 2018). "Moreover, studies on cervical cancer showed that in a normal cervix, Notch-1 is more commonly membrane-localized than in a cancerous cervix." (PMID 30038662, 2018). "We also observed the effects of Notch1 on certain genes in cervical cancer Hela cells." (PMID 28423575, 2017). "Notch1 activation has also been reported to induce the cervical cancer cell line HeLa to undergo apoptosis, growth arrest, and tumor growth suppression in vivo, although the role of JAG1 has not specifically been investigated within this tumor-suppressor context." (PMID 25309874, 2014). "Similarly, in keratinocyte-derived tumors, like cutaneous squamous cell carcinomas (SCCs), basal cell carcinomas (BCCs) and late stage cervical carcinomas, Notch1 expression is decreased to a substantially greater extent than Notch2." (PMID 20442780, 2010).
cervical carcinoma (continued). "Using immunohistochemical techniques, we show that there is expression of both Notch1 and RhoC in the same areas of cervical carcinoma tissue sections with significant correlation while there was negligible expression of the proteins in the normal cervical tissue sections." (PMID 19953094, 2010). "Activating mutations have been reported in human T-ALL Notch1; however, limited sequencing of a similar region in Notch1 alleles of cervical carcinoma suggests the absence of such a mutation (D Subramanyam and S Krishna, unpublished data)." (PMID 19953094, 2010). "Furthermore, CaSki cells are phenotypically similar to most cervical cancers with regard to its expression of Jagged1, features of activated Notch1 and PI3K signalling and dependence on Notch1 signalling for growth and survival." (PMID 19953094, 2010). "The objective is to further delineate the mechanism of action of NOTCH1 in cervical cancer, and provide a novel theoretical foundation and potential therapeutic targets for overcoming radiotherapy resistance and optimizing clinical treatment strategies for cervical cancer." (PMID 41306984, 2025). "However, overexpression of has-miR-449a significantly improved the radiosensitivity of cervical cancer by inhibiting NOTCH1 expression in the current study, indicating that the mechanism of action of has-miR-449a may vary across different cancer types." (PMID 41306984, 2025). "Furthermore, in the FCH cohort, patients in the NOTCH1 high-expression group had significantly shorter OS than those in the low-expression group, which further verified the clinical significance of NOTCH1 as a poor prognostic marker for cervical cancer." (PMID 41306984, 2025). "However, NOTCH1’s mechanisms in cervical cancer progression and radiotherapy resistance, as well as its interaction with key molecules, remain unclear." (PMID 41306984, 2025). "Our data suggest that the loss of nuclear NOTCH1 but not NUMB might be an independent predictor of malignancy in cervical cancer." (PMID 29721172, 2018). "Curcumin-mediated photodynamic therapy (PDT) significantly downregulates Notch1 and its downstream effectors NF-κB and VEGF in both in vitro and in vivo cervical cancer models." (PMID 41602823, 2026). "NOTCH1, one of the core transmembrane receptors of the NOTCH signaling pathway, is highly expressed in various tumor cells, including cervical cancer cells." (PMID 41306984, 2025). "Finally, NOTCH1 could reduce the radiosensitivity of cervical cancer cells to radiotherapy both in vitro and in vivo; whereas has-miR-449a, as an upstream regulatory miRNA of NOTCH1, could inhibit cervical cancer cell proliferation and enhance radiosensitivity by inhibiting NOTCH1 expression." (PMID 41306984, 2025). "Notch1 induced cyclin D1 and CDK2 activity, two key molecules of cell proliferation in cervical cancer cells." (PMID 35740666, 2022). "The co-localization of Notch1/cleaved Notch/Hes1 and FTS spectacles the importance of FTS in mediating the Notch signaling in cervical cancer cells." (PMID 34765546, 2021). "The HPV16‐binding human cervical cancer SiHa cell line was used to silence the expression of HPV16 E6/E7 gene by RNA interference, and the expression of p16INK4a, Notch1, and hTERC genes and protein expression levels were detected by RT‐PCR and Western blot." (PMID 31976596, 2020). "The analysis of the TCGA data by the GEPIA webtool revealed the strong positive correlation between AhR and Notch1 (R = 0.39, p = 2.5 × 10−12) and between ARNT and Notch1 (R = 0.54, p = 0) in cervical cancer patients." (PMID 32545442, 2020). "It was confirmed that the p16INK4a, Notch1, and hTERC genes are closely related to HPV‐infected cervical precancerous lesions and cervical cancer." (PMID 31976596, 2020).
cervical carcinoma (continued). "Taken together, these results suggest that Notch1 and IKKα cooperatively promote NF-κB transcriptional activity in MDA-MB-231 cells as they do in cervical cancer cells." (PMID 30564555, 2018). "Our previous study showed the effects of Notch1 on certain genes such as NR4A2, p63 in cervical cancer Hela cells." (PMID 28423575, 2017). "In the present study we showed that reduction of RKIP expression significantly increased production of an active form of Notch1, NICD, and subsequently promoted the metastatic ability of lung and cervical cancer cells." (PMID 26716415, 2016). "In this study, activation of Notch1 (NICD production) in lung and cervical cancer cell lines also promotes tumor invasion/migration and upregulation of EMT-related proteins." (PMID 26716415, 2016). "Expression of microRNA-34a, which downregulates both Notch1 and JAG1, inhibits abnormal cell growth and suppresses cervical cancer invasiveness by repressing Notch-JAG1 signaling." (PMID 25309874, 2014). "In addition, Notch1 promoter methylation increases with age, severity of the disease, and HPV infection in patients with cervical cancer." (PMID 38279330, 2024). "Glycyrrhizin modulates Notch signaling through the action of Notch1 and the ligand Jagged-1, which reduces the expression of its downstream target gene HES-1 and cyclin D1, which is one of the important proteins that activate NICD in cervical cancer." (PMID 39206407, 2024). "Among North Indian patients with cervical cancer, the methylation rate of Notch1 and Notch3 promoters is notably elevated compared to healthy tissues, accompanied by a downregulation in protein expression." (PMID 38279330, 2024). "Notch1 expression was elevated in paclitaxel-resistant cervical cancer cells compared to non-resistant cells, and silencing the NOTCH1 gene reversed EMT, indicating that Notch1 is involved in the paclitaxel resistance process in cervical cancer." (PMID 35684449, 2022). "We further discovered that the reduction of IDO1 expression also inhibited Notch1 activation and the addition of kynurenine, the first breakdown product of IDO1 mediated tryptophan metabolism, increased the self-renewal capability of cervical cancer cells." (PMID 32545442, 2020). "The findings suggest that Notch-1 and Notch-3 may play an important role with synergistic effect of HPV in regulating development and proliferation of cervical cancer through the deregulation of Notch signalling." (PMID 31417656, 2019). "Although many cervical tumors are consistently characterized by features associated with misregulation of Jagged1-induced Notch signaling, expression of Notch1 is remarkably reduced or absent in some invasive cervical cancer tissues." (PMID 26716415, 2016). "Epithelial transformation by KLF4 requires Notch1 but not canonical Notch1 signaling, and Notch signaling plays an important role in the development and progression of cervical cancer." (PMID 24551169, 2014). "Further study shows that the expression of activated Notch1 causes strong growth inhibition of HPV-positive, but not HPV-negative, cervical carcinoma cells." (PMID 23409141, 2013). "In supporting such assumption, it has been reported that the expression of Notch1 is markedly reduced or absent in invasive cervical cancers." (PMID 23409141, 2013). "Notch-1, an advanced preserved signaling pathway that controls interactions between adjoining cells and NF-κB, could be the targets of the curcumin-PDT combination in the success of cervical cancer therapy in women." (PMID 34683855, 2021). "Consequently, Notch1 activity was absent in their cohort of invasive cervical cancer samples." (PMID 25309874, 2014).
lymphoma (71 papers, 2009 to 2025). A malignant (clonal) proliferation of B- lymphocytes or T- lymphocytes which involves the lymph nodes, bone marrow and/or extranodal sites. "NOTCH1 mutations are found in B-cell tumors; and include chronic lymphocytic leukemia/lymphoma, mantle cell lymphoma and diffuse large B-cell lymphoma (DLBCL)." (PMID 39951437, 2025). "Deregulated Notch1 signaling has been implicated in various types of cancer including T-cell lymphoblastic leukemia/lymphoma." (PMID 36768603, 2023). "Aberrant activation in the Notch1 signaling pathway has been demonstrated to be implicated in hematological malignancies including T-cell lymphoblastic leukemia/lymphoma." (PMID 36768603, 2023). "The truncation of Notch1 can generate lymphomas by the loss of the PEST domain located in the 3′ end of the Notch1 gene, which leads to an enhanced protein half-life and, therefore, longer activity as a transcription factor in the nucleus." (PMID 35852337, 2022). "In total, 15 activating Notch1 mutations were detected in 9 of 15 lymphomas (60%) and among these, five tumors had more than one mutation of the Notch1 gene." (PMID 34771656, 2021). "Our results showed that the NOTCH1 mutations were significantly associated with low blood monocyte count and high lymphoma/monocyte ratio (LMR)." (PMID 34956871, 2021). "NOTCH1 mutations were significantly associated with lower blood monocyte counts (P=0.031) but higher lymphoma/monocyte ratio (P=0.02) and higher hemoglobin levels (P=0.006)." (PMID 34956871, 2021). "Clinically, NOTCH1 mutations identify patients with a worse prognosis in terms of therapy responses and with higher risk of disease transformation into an aggressive lymphoma." (PMID 30534535, 2018). "As expected, frequent NICD1 staining was observed in T lymphoblastic leukemia/lymphoma, a tumor in which activating NOTCH1 mutations are common." (PMID 23825651, 2013). "As high Lef1 expression is already present in pre-leukemic samples, it is likely that deregulated Wnt signaling predisposes thymocytes to induction of activating somatic mutations in Notch1, which subsequently accelerate lymphoma development." (PMID 23185135, 2012). "Loss of Tcf1 as repressor of Lef1 leads to high Wnt activity and is the initiating event in lymphoma development, which is exacerbated by activating Notch1 mutations." (PMID 23185135, 2012). "Although mutations in the Notch1 gene have been detected in various T cell leukemias or lymphomas triggered by loss of function of transcription factors or increases in signaling transduction, the exact role of these mutants is not well understood." (PMID 19688092, 2009). "BCL6 Corepressor (Bcor) loss drives alterations in the B-cell compartment, promotes the transformation of CLL into aggressive lymphoma, and frequently co-occurs with mutated NOTCH1 which is a hallmark of RT, suggesting the therapeutic potential of targeting Bcor and NOTCH1 in RT." (PMID 40565027, 2025). "By contrast, in NOTCH1 pG4, 570 out of 618 variants consisted of a 2-bp deletion at a single site across from a hairpin bulge, and essentially all variants were discovered from targeted sequencing screens in patients with lymphoma." (PMID 39341500, 2024).